MYC (MYC proto-oncogene, bHLH transcription factor)
Diseases named in the same sentence as MYC in open-access papers (continued):
Sharing a sentence is not in itself a finding about the gene and the disease.
colorectal tumors (35 papers, 2003 to 2025). "Deletion of MYC rescues the colorectal tumor phenotype of the Apc-deficient mouse model 11, suggesting an important role of MYC in colorectal tumorigenesis." (PMID 32549753, 2020). "Gain in the MYC gene was seen throughout the cancer type, and c2 was uniquely characterized by loss of the chromosome 20 p-arm, which harbors the hsa-mir-103–2 previously reported to be downregulated in colorectal tumors." (PMID 33272320, 2020). "Conversely, depletion of MYC in colorectal tumors results in significant impairment of global translation." (PMID 38067212, 2023). "Collectively, these findings suggest that c-MYC S405 phosphorylation is essential for NEK8-mediated colorectal tumor progression." (PMID 37596667, 2023). "BOP1 was found overexpressed in the colorectal tumor tissues and its expression level was related with copy number variation of MYC." (PMID 35222794, 2022). "The proto-oncogene MYC is the proposed master regulator of colorectal tumour metabolism, including a reversed Warburg effect." (PMID 35160173, 2022). "Activation of IL-6/p-STAT3/c-MYC signaling was demonstrated to enhance colorectal tumor growth in a TLR4-dependent manner." (PMID 34898475, 2021). "That together with the HIF targets signature evidence suggest that the MYC-driven colorectal tumours are of oxidative nature and that their oxidative status is not significantly different from that of normal tissues." (PMID 32366892, 2020). "Previous metabolomics study discovered that palmitate and oleate levels increase in MYC-driven colorectal tumors, while enzymes involving fatty acid oxidation, including ACADS, are down-regulated." (PMID 31623618, 2019). "For example, MYC was involved in the proliferation and oncogenesis of colorectal tumor cells through targeting lncRNAs CDKN1A and CDKN2B57." (PMID 30518750, 2018). "We sought to assess the role of oncogenic KRAS in the regulation of MYC expression in cell lines derived from lung and colorectal tumors and the effects of MYC on cellular cytotoxicity and drug sensitivity according to KRAS mutation status." (PMID 28152508, 2017). "Of significant interest in studies performed here is the observation that MYC expression is elevated in TG versus NTG cells from xenogeneic colorectal tumors, and that MYC levels are further increased in residual cells with the CoCSC phenotype." (PMID 18560594, 2008). "Moreover, it has been demonstrated that a lncRNA, CCAT1-L, located in a SE and close to MYC, is transcribed from 515 kb upstream of MYC in human colorectal tumors." (PMID 37501079, 2023). "Indeed, eIF4A inhibition has been reported as a promising strategy to reduce MYC expression in colorectal tumors, and the possibility of metformin directly inhibiting eIF4A activity cannot be excluded." (PMID 30221473, 2018). "Similarly, c-Myc was noticeably more concentrated in the nucleus of colorectal tumor cells of CPA-treated mice, consistent with the increased frequency of TG cells and elevated MYC expression within this resilient population." (PMID 18560594, 2008). "Therefore, MYC is likely to play an intrinsic role in the progression of colorectal tumours." (PMID 38637125, 2024). "The functional relevance of these data suggesting that MYC regulates ITGA1 expression at the transcriptional level was strengthened by the finding that MYC and ITGA1 protein expressions are found to be correlated in more than 72% of the colorectal tumour samples analyzed." (PMID 27014720, 2016). "Further, despite the fact that we could not show consistent regulation of c-MYC protein levels by BCL-3 in any of the cell lines (data not shown) the two studies describe potentially complementary mechanisms that clearly emphasise the importance of BCL-3 expression in colorectal tumour cell growth." (PMID 26033966, 2016).
esophageal cancer (35 papers, 2011 to 2025). A primary or metastatic malignant neoplasm involving the esophagus. "Lastly, esophageal cancer often exhibits intrachromosomal amplification of MYC, ERBB2, EGFR, RB1, GATA4/6, CCND1, RTK and MDM2 as well as ecDNA-associated amplification of MYC and MDM2." (PMID 41415205, 2025). "Phosphorylated ANXA2 interacts with MYC and inhibits ubiquitin-dependent proteasomal degradation of MYC protein in esophageal cancer." (PMID 33004065, 2020). "ANXA2 promoted esophageal cancer progression by activating MYC-HIF-1α-VEGF axis." (PMID 38429756, 2024). "In esophageal cancer, MYC is aberrantly activated due to MYC gene amplification." (PMID 36969025, 2023). "For example, approximately 45% of driver events in esophageal cancer included focal amplifications in cell cycle genes such as CCND1/2/3 and CDK4/6/9, in addition to amplifications in ERBB2, KRAS, MYC." (PMID 33889297, 2021). "The results showed a significant correlation between the expression levels of SPINK5 and β‐catenin (CTNNB1), LRP5, LRP6, DVL3, LEF1, AXIN2, MYC, and cyclin D1 (CCND1) in esophageal cancer." (PMID 30868765, 2019). "This research group have developed a phase II trial of ibrutinib in patients with MYC and/or HER2 amplified esophageal cancer is currently recruiting based on this (NCT02884453)." (PMID 29561760, 2018). "In addition, the expression of cyclin D1, MYC, MMP2, and molecules involved in the NF‐κB signaling pathway was increased in esophageal cancer cells, similarly as observed for PD‐L1." (PMID 40790948, 2025). "Furthermore, in esophageal cancer, ANXA2 expression was overexpressed and promoted the tumor progression by activating the MYC/HIF1A/VEGF signaling pathway." (PMID 35977942, 2022). "Ibrutinib elicited G1 cell cycle arrest and apoptosis in both MYC and HER2 amplified tumors, suggesting this drug could be used to treat biomarker-selected groups of patients with esophageal cancer." (PMID 29561760, 2018). "The role of MYC in the pathogenesis of esophageal cancer is not well defined and additional research is required." (PMID 25784931, 2015). "Consistent with reports that identified c-MYC and Cyclin D1 as two important targets of the β-catenin/TCF transcription complex, our results demonstrated that t-DARPP-mediated activation of β-catenin/TCF leads to up-regulation of c-MYC and Cyclin D1 in gastric and esophageal cancer cells." (PMID 21447180, 2011).
non-Hodgkin lymphoma (35 papers, 2012 to 2026). Distinct from Hodgkin lymphoma both morphologically and biologically, non-Hodgkin lymphoma (NHL) is characterized by the absence of Reed-Sternberg cells, can occur at any age, and usually presents as a localized or generalized lymphadenopathy associated with fever and weight loss. "Recent studies have shown that GNAQ mutations appear repeatedly in certain types of non-Hodgkin lymphoma, and other studies have suggested that MYC alterations are associated with aggressive non-Hodgkin lymphoma or a poor prognosis of uveal melanoma." (PMID 34682867, 2021). "With this in mind, MYC was targeted with an ellipticine derivative that causes downregulation of MYC expression in non-Hodgkin lymphoma." (PMID 32098397, 2020). "Among B-cell tumors, MYC has been historically implicated in the molecular pathogenesis of aggressive non-Hodgkin lymphomas." (PMID 28424416, 2017). "Burkitt lymphoma is a highly aggressive rare subtype of non-Hodgkin lymphoma (NHL) with the genetic hallmark of MYC gene translocation." (PMID 35979854, 2021). "To test this, we studied DLBCL, an aggressive non-Hodgkin lymphoma characterized by high MYC activity." (PMID 36897988, 2023). "Our DNAi approach enables specific and direct downregulation of MYC expression, with potential efficacy in MYC-reliant cancers, such as non-Hodgkins lymphoma (NHL)." (PMID 34577013, 2021). "SC-1, a follicular non-Hodgkin lymphoma subtype harboring chromosomal rearrangements in MYC, BCL6 and BCL2, was among the cell lines found to be most sensitive to (−)-CR-1-31-b and CMLD011580." (PMID 30718665, 2019). "The small molecule GQC-05 has previously been described as having G4 binding properties with a preference for the (NHE)III G-quadruplex on the MYC promoter sequence and demonstrated decreased MYC gene expression in non-Hodgkin’s lymphoma cells." (PMID 31881855, 2019). "Tumor cells overexpressing MYC, such as non-Hodgkin lymphoma (NHL) cells, rely on glutamine metabolism as a fuel for the TCA cycle in the tumor microenvironment with its specific nutrient supply." (PMID 31454887, 2019). "The most frequently determined markers in the non-Hodgkin lymphoma are CD20, CD3, CD5, CD10, BCL6, BCL2, Ki-67, MYC, and cyclin D1." (PMID 40142344, 2025). "Burkitt’s lymphoma (BL) is a highly aggressive non-Hodgkin lymphoma (NHL), which is driven by the characteristic translocation of the MYC oncogene." (PMID 30104685, 2018). "IHC analysis using a non-Hodgkin lymphoma panel was performed, and subtyping was done using the Hans algorithm to classify cases as germinal center B-cell-like (GCB) or non-germinal center B. Double expressor status was defined by IHC expression thresholds for BCL2 and c-MYC." (PMID 41458681, 2025). "This compound class has been reported to be active in a number of diseases dependent on either MYC or MYCN, including neuroblastoma, medulloblastoma, multiple myeloma, and non-Hodgkin Lymphoma (NHL), to name a few." (PMID 25072021, 2014).
viral infection (35 papers, 2012 to 2026). "However, MYC has been implicated in the regulation of the development of memory CD8(+) T cells in response to viral infection." (PMID 34940755, 2021). "Some data support the most accepted mechanism, which is that viral infection of B cells in the lymph nodes is the triggering event that leads to MYC translocation followed by lymphomagenesis." (PMID 39766110, 2024). "Among the increased transcription factor IRFs, STATs, MYC, NFKB1, NFKB2, and NF-kappa B RELA have been implicated in viral infection." (PMID 34940755, 2021). "Based on our data regarding PKR, it would be most reasonable to interpret that nc886 knockdown was a mimicry of viral infection and accordingly induced MYC and FOS as well as genes related to inflammation and infection such as oncogenic NF-κB." (PMID 25004084, 2014). "For instance, the expression of FOS and MYC oncogenes are induced by growth factors, oxidative stress, dsRNA, and viral infection." (PMID 25004084, 2014). "As in c-MYC, dramatic NPM1 expression was induced in EBV positively infected B cells after three days of viral infection, and both EBNA2 and EBNALP were implicated in the transactivation of the NPM1 promoter." (PMID 23271972, 2012). "Therefore, MYC would enhance viral infection on one hand but prevent the lytic cycle of infected cells on the other hand, thus contributing to the latency I program typical of BL cells." (PMID 39766110, 2024). "The siRNAs effectively knocked down the expression of these genes, and knockdown of MYC significantly increased M1 virus infection, indicating that MYC might be a key factor suppressed by lonidamine signaling to promote M1 virus infection and replication." (PMID 33292203, 2020). "Therefore, the studies reviewed revealed that MYC and miRNAs have a very complex interaction in GC that can be affected by external factors, such as bacterial and virus infection." (PMID 32150871, 2020). "To further identify the specific IRG that inhibits viral infection, we used siRNAs to knock down the three genes identified above (ADM11, SECTM1, and MYC) in the HCT 116 cell line." (PMID 33292203, 2020). "Accordingly, we observed a pronounced induction of both c-MYC and NPM1 in EBV positively infected B lymphocytes throughout the duration of viral infection." (PMID 23271972, 2012). "In fact, it has been described that Hepatitis B virus genome integrates in the region located between MYC and PVT-1 in 12.4% of HCCs that develop early after viral infection and that viral integration correlates with upregulation of MYC and PVT-1, and, most probably, with the development of HCC." (PMID 29033906, 2017). "Unfortunately, we were also unable to determine whether overexpression of MYC could restore ASC differentiation in IRF5 knockdown cells due to limitiations in transfection and/or viral infection efficiency." (PMID 29367853, 2017). "Although adenovirus-encoded E4ORF1 activation of MYC is responsible for the reported changes in glucose and glutamine metabolism during viral infection, the reduced respiration in adenovirus-infected cells seems to occur independent of E4ORF1 and MYC." (PMID 31319842, 2019). "The occurrence of it may be related to MYC, P63, and MED24 as well as Wnt, MAPK, and PI3K signaling pathways, but it has no connection with environmental factors and viral infection, such as Epstein-Barr virus and human papillomavirus." (PMID 36687409, 2022).
chronic lymphocytic leukemia (31 papers, 2011 to 2025). "FARP2 has been reported as a potential regulator of chronic lymphocytic leukemia pathogenesis that influences protein activity encoded by MYC gene." (PMID 34373545, 2021). "This review examines the pivotal role of c-MYC in Chronic Lymphocytic Leukemia (CLL), focusing on how its overexpression leads to increased genetic instability, thereby accelerating disease progression." (PMID 39594704, 2024). "This review explores the role of c-MYC in Chronic Lymphocytic Leukemia (CLL) and its impact on genetic instability and disease progression." (PMID 39594704, 2024). "Secondary PBL transformation from CLL (chronic lymphocytic leukemia) or FL also can be found MYC translocations." (PMID 26416427, 2015). "Furthermore, the MYC-mediated miR-29 repression mechanism for the therapy of aggressive B-cell malignancies (B-cell malignancies is the synonym of chronic lymphocytic leukemia according to Medical Subject Headings (MeSH)) by applying the HDAC3 and EZH2 as therapeutic targets was reported." (PMID 28340554, 2017). "Genomic profiling of Richter's syndrome, which represents a transformation of chronic lymphocytic leukemia (CLL) to aggressive lymphoma and is mostly represented by DLBCL, with a postgerminal center phenotype, shows a 13q amplification which encodes the miR-17~92 cluster which interacts with c-MYC." (PMID 21461378, 2011). "STAT1, c-Fos, c-MYC, and Bcl-2 positively correlate with CTLA-4 expression in chronic lymphocytic leukemia (CLL)." (PMID 34088360, 2021). "To determine whether the inverse relationship between MYC and PDCD4 expression is also observed in vivo we performed dual-color IHC of LN from patients with CLL/small lymphocytic lymphoma." (PMID 35306137, 2022).
colon adenocarcinoma (31 papers, 2009 to 2026). "Abnormal expression of MYC is generally associated with a poor colon adenocarcinoma prognosis." (PMID 35847359, 2022). "Two earlier studies using fibroblast and colon adenocarcinoma lines found that MYC promotes N-glycan branching and display of the glycan sialyl-Lewisx, respectively, although the physiological relevance of these changes was unclear." (PMID 36897988, 2023). "Prior in vitro studies of fibroblasts and colon adenocarcinoma lines found that MYC promotes N-glycan branching and display of the glycan sialyl-Lewisx, respectively." (PMID 36897988, 2023). "In fact, similar to our finding in CRC, another report studying high-grade colon adenocarcinoma cells has examined the widespread c-MYC." (PMID 34623601, 2022). "Pan-cancer analysis showed that MYC expression was significantly higher in colon adenocarcinoma and rectum adenocarcinoma compared with adjacent normal tissues." (PMID 33193630, 2020). "Considering that α1 subunit/ITGA1 expression is correlated with MYC in more than 70% of colon adenocarcinomas, we postulated that the integrin α1β1 has a pro-tumoral contribution to CRC." (PMID 28933766, 2017). "We assessed one-dimensional (1D) H3K27ac ChIP enrichment detected by HiChIP and observed H3K27ac enrichment either at regulatory elements located 5′ of MYC in cancer types such as colon adenocarcinoma (COAD) or at 3′ regulatory elements as in liver hepatocellular carcinoma (LIHC)." (PMID 40355593, 2025). "Aloin and piperine can inhibit proliferation of (colo)rectal cancer cells; the genes MYC and BIRC5, the expression of which is decreased by the two compounds, are otherwise overexpressed in colon adenocarcinoma." (PMID 34422220, 2021). "Our analysis using the TCGA database revealed that EZH2 and MYC were upregulated across multiple human tumors, including stomach adenocarcinoma (STAD), colon adenocarcinoma (COAD), and rectum adenocarcinoma (READ)." (PMID 39823459, 2025).
oral cancer (31 papers, 2009 to 2025). "Smoking and alcohol use cause genetic mutations in the proto-oncogene, MYC, which promotes oral cancer." (PMID 37504265, 2023). "Reports suggest that MYC is found to be associated with oral cancer progression." (PMID 36708238, 2023). "Furthermore, our study clearly demonstrates miR-31-induced downregulation of the cell-cycle regulatory molecules, including the well-established proto-oncogenes cyclin D1 (CCND1) and c-MYC, presumably linked to a delay in the cell cycle of oral cancer cells." (PMID 33007980, 2020). "In another study, F. nucleatum upregulated MMP1, MMP9, and IL-8 in oral cancer cell lines, and the infected cell lines showed overexpression of cell survival markers, such as MYC, JAK1 and STAT3, and EMT markers (ZEB1 and TGF-β)." (PMID 40002861, 2025). "METTL3, a m6A writer, enhances c-MYC stability by modifying m6A levels in oral carcinoma, whereas YTHDF2, a m6A reader, promotes its degradation." (PMID 41167308, 2025). "CircUHRF1, an oral cancer-associated circRNA, sponges miR-526b-5p to positively regulate MYC protein expression to promote oral cancer progression." (PMID 39155279, 2024). "In a preliminary in vitro validation experiment, infection of SCC25 oral cancer cells with C. acnes resulted in upregulation of MYC expression." (PMID 37377901, 2023). "c-MYC, one of the most frequently inordinate oncogenes, is highly expressed in several malignancies including oral cancers." (PMID 34268253, 2021). "Accordingly, we measured the expression of STAT3, JAK1, and MYC in three oral cancer cell lines (OQ01, HN, BHY) after polymicrobial infection with the combination of P. gingivalis, F. nucleatum, T. denticola, and T. forsythia by qRT-PCR." (PMID 33391626, 2020). "For patients with T3 or T4 oral cancer, MYC gene expression is related to the likelihood of survival and can serve as a key biomarker for treatment." (PMID 33142921, 2020). "It should be pointed out that previous reports showed that chromosome 8 CNAs are common alterations in oral cancers and that MYC amplification, whose locus is contained in the 8q24.3 region, plays an oncogenic role." (PMID 26540282, 2015). "Several reports have indeed confirmed the genetic alterations of the MYC gene in oral cancer." (PMID 37893092, 2023). "The overexpression of the MYC gene has also been noted in most patients with oral cancer." (PMID 33142921, 2020). "Thus, by controlling METTL3/HIF-1/MYC signaling in oral cancer, our investigations reveal a previously unidentified connection between arecoline and cisplatin resistance that may help develop strategies to overcome the challenge of cisplatin resistance in OSCC patients." (PMID 36429032, 2022). "In addition to a proteasome inhibitor, the DSF-Cu (I and II) complex might decrease the dominant-negative effect of MYC-nick to elevate its cytotoxicity in oral cancers." (PMID 36012403, 2022).